HNF1B (HNF1 homeobox B)
Diseases named in the same sentence as HNF1B in open-access papers (continued):
Sharing a sentence is not in itself a finding about the gene and the disease.
Glucose intolerance (3 papers, 2015 to 2024). Glucose intolerance (GI) can be defined as dysglycemia that comprises both prediabetes and diabetes. "In kidney cells, HNF1B regulates renal tubulogenesis while a reduction of HNF1B in the liver induces glucose intolerance, impairs insulin sensitivity and causes gluconeogenesis." (PMID 35884482, 2022). "HNF1B is targeted by miR-802-dependent silencing, and it has been revealed that a short hairpin RNA (shRNA)-mediated reduction in HNF1B in the liver leads to glucose intolerance, damage to insulin signaling, and increased hepatic gluconeogenesis." (PMID 39337310, 2024).
hyperlipidemia (3 papers, 2023 to 2025). "The pathogenicity also confirms the presence of the mutation in two affected family members from Croatia, as well as the coexistence of other extrapancreatic traits associated with mutations of the HNF1B gene (hyperlipidemia and hepatic lesion, dyslexia)." (PMID 37511676, 2023).
invasive breast carcinoma (3 papers, 2009 to 2023). A carcinoma that infiltrates the breast parenchyma. "In bladder urothelial carcinoma (BLCA), breast invasive carcinoma (BRCA), kidney renal clear cell carcinoma (KIRC), brain lower grade glioma (LGG) and mesothelioma (MESO), the expression level of HNF1B also influenced the prognostic value of B-cell infiltration levels." (PMID 33173410, 2020).
learning disabilities (3 papers, 2023 to 2024). "Only one study found NDDs in patients with a mutation of HNF1B, two patients were reported to have learning disorder (15%)." (PMID 36969268, 2023). "The patient in the single case study with a mutation of HNF1B was reported to have a learning disorder." (PMID 36969268, 2023).
liver dysfunction (3 papers, 2015 to 2024). "Liver dysfunction, characterized by an asymptomatic elevation in liver enzyme levels, is common in patients with HNF1B mutations." (PMID 39337310, 2024).
medullary sponge kidney (3 papers, 2021 to 2024). Medullary sponge kidney (MSK) is a birth defect of the tubules - tiny tubes inside the kidneys. "Lastly, other types of non-hereditary and hereditary CyKD, which are not included in this study, are complex renal cyst, cystic renal tumor, obstructive cystic dysplasia, medullary sponge kidney, glomerulocystic kidney disease (GCKD) HNF1B/TCF2-associated disease, and Von Hippel–Lindau syndrome." (PMID 38671609, 2024).
oncocytoma (3 papers, 2007 to 2020). "In the present study, ChRCC demonstrated total loss of HNF1β (24/30–80%), but partial loss in 20%, while no mimickers including oncocytoma demonstrated HNF1β loss." (PMID 32150988, 2020). "In contrast, CK7-/c-kit+/HNF-1β+ staining can suggest oncocytoma." (PMID 32150988, 2020).
Polyhydramnios (3 papers, 2020 to 2023). The presence of excess amniotic fluid in the uterus during pregnancy. "Furthermore, Leire Gondra reported that HNF1B mutation represents the leading cause of polyhydramnios associated with hyperechogenic (and sometimes enlarged) kidneys." (PMID 32779812, 2020). "Inefficient expression of HNF1B in the region of 17q12 is known to be a predominant factor leading to renal disease, which may result in fetal polyuria and polyhydramnios." (PMID 35354480, 2022).
renal fibrosis (3 papers, 2016 to 2021). A final common manifestation of a wide variety of chronic kidney diseases characterized by glomerulosclerosis and tubulointerstitial fibrosis. "The results suggest that the suppression of HNF-1β in TECs is associated with the dedifferentiation of TECs and the accumulation of the mesenchymal cells, including fibroblasts into the tubular interstitium in the kidney of in vivo renal fibrosis model." (PMID 27196561, 2016). "Furthermore, the expression of HNF-1β in TECs was downregulated in association with the development of renal fibrosis in in vivo model." (PMID 27196561, 2016). "In mouse renal fibrosis model, unilateral ureteral obstruction model, HNF-1β expression in the TECs of the kidney was suppressed with fibrosis progression." (PMID 27196561, 2016). "In the present study, we also showed that expression of the HNF-1β in the kidneys was suppressed in renal fibrosis model, which were elicited by UUO." (PMID 27196561, 2016). "Histological study of the renal fibrosis model also showed the downregulation of the HNF-1β, which was expressed in all nephron segments of the normal kidneys." (PMID 27196561, 2016). "Finally, in the context of renal fibrosis caused by the loss of HNF-1β, HNF-1β deficient renal epithelial cells mIMCD3 showed upregulated mesenchymal traits relative to wild-type cells, as again captured by the KS, 76GS, and MLR scores (GSE97770)." (PMID 35053177, 2021). "The suppression of HNF-1β was observed prior to the significant development of the renal fibrosis." (PMID 27196561, 2016). "Although the inhibitory effect of HNF-1β upregulation on renal fibrosis progression remains to be elucidated, the re-epithelialization by regulation of HNF-1β may represent an epochal therapeutic strategy for renal fibrosis." (PMID 27196561, 2016). "In contrast, we found that HNF-1β induced the re-epithelialization of hRPTECs dedifferentiated by TGF-β1, which plays a pivotal role in the pathogenesis of renal fibrosis." (PMID 27196561, 2016). "In conclusion, HNF-1β suppression in TECs is a crucial event for the dedifferentiation of TECs, and the upregulation of HNF-1β in TECs has a potential to restore the dedifferentiated TECs into their normal state, leading to the attenuation of renal fibrosis." (PMID 27196561, 2016).
testicular germ cell tumor (3 papers, 2013 to 2020). A germ cell tumor arising from the testis. "Another research discovered HNF1B rs7501939 was a susceptibility locus for testicular germ cell tumor." (PMID 30053805, 2018). "The positive correlation between HNF1B expression and monocyte infiltration level was found in liver hepatocellular carcinoma (LIHC, r= 0.339, p = 1.07e-10) and Testicular Germ Cell Tumors (TGCT, r=0.363, p=6.25e-06)." (PMID 33173410, 2020).
yolk sac tumor (3 papers, 2013 to 2024). A non-seminomatous malignant germ cell tumor composed of primitive germ cells. "Other studies had shown that HNF1β was significantly expressed in yolk sac tumor with a sensitivity of 100% and a specificity of 80%." (PMID 39711964, 2024).
alcoholic liver diseases (2 papers, 2015 to 2022). A disorder caused by damage to the liver parenchyma due to alcohol consumption. "To further investigate the role of miR-141/200c in vivo in regulating TG secretion in alcoholic liver disease, we examined protein levels of HNF1B, MTTP, and APOO in WT- and KO-mice–fed CB or EB." (PMID 35460694, 2022). "Immunostaining of patients with advanced alcoholic liver disease showed that ductular reaction cells were positive for HNF1β, whereas HNF1β was not expressed in mature hepatocytes." (PMID 26464794, 2015).
Bartter syndrome type 3 (2 papers, 2012 to 2019). "Both genes are involved in the pathophysiology of Bartters syndrome types III and IV and renal diabetes insipidus, but both these diseases are not known to be included in patients with HNF1B deficiency." (PMID 22438943, 2012).
biliary tract cancer (2 papers, 2015). "Study shows expression of HNF1β is relatively low in BTC, and HNF1β is nonessential in the biliary tract cancers differentiation and maintenance." (PMID 26464794, 2015).
breast tumors (2 papers, 2009 to 2021). "To corroborate the DCIS-specific methylation profiles of TLX1, CGI 7:48, HOXB13, and HNF1B, we then extended the COBRA analysis to a series of primary breast tumors of different histological type and stage." (PMID 19250546, 2009). "Moreover, in breast tumours, methylation of homeobox genes including HOXB13 and HNF1B, CpG islands has been found to be significant and more pronounced compared to normal samples." (PMID 33580750, 2021).
Cirrhosis (2 papers, 2017 to 2023). A chronic disorder of the liver in which liver tissue becomes scarred and is partially replaced by regenerative nodules and fibrotic tissue resulting in loss of liver function. "In the HCC cohort, the following factors had a significant effect on DFS: higher tumour HNF-1β expression (P = 0.001), higher tumour size (P = 0.010), higher TNM stage (P = 0.005), higher Edmondson grade (P = 0.021), and cirrhosis (P = 0.001)." (PMID 28684878, 2017).
cystinuria (2 papers, 2012 to 2024). Cystinuria is a renal tubular amino acid transport disorder characterized by recurrent formation of kidneys cystine stones. "In human patients cystinuria is attended by mutations in SLC3A1 and SLC7A9, but it is not known whether these defects are present in carriers of HNF1β mutation." (PMID 22438943, 2012).
diabetic ketoacidosis (2 papers, 2024 to 2025). The metabolic condition resulted from uncontrolled diabetes mellitus, in which the shift of acid-base status of the body toward the acid side because of loss of base or retention of acids other than carbonic acid is accompanied by the accumulation of ketone bodies in body tissues and fluids. "There was one patient with the INS variant, two with the ABCC8 variant and one with the HNF1B variant who had diabetic ketoacidosis (DKA) at initial diagnosis." (PMID 40303944, 2025).
endometrioid tumor (2 papers, 2015 to 2023). A benign, borderline, or malignant epithelial tumor of the female reproductive system characterized by the presence of glands and/or cysts lined by neoplastic cells that resemble endometrial cells. "There was evidence for association between genotype and HNF1B expression levels in endometrioid tumors for rs11263763 (P = 1.3 × 10−2), rs11658063 (P = 5.0 × 10−3) and marginally so for rs11651755 (P = 8.3 × 10−2)." (PMID 25378557, 2015). "We also tested the allelic effect of rs11263763 and rs11658063 on HNF1B expression in non-endometrioid tumors (total N = 52), and similarly identified eQTLs for both rs11263763 (P = 3.0 × 10−2) and rs1165806 (P = 4.8 × 10−2)." (PMID 25378557, 2015). "Conversely, the absence of HNF-1β expression in endometrioid histology and in ovarian cortical inclusion cysts would support the metaplastic transformation of the inclusion cysts into a Müllerian epithelium as a precursor of endometrioid tumor development." (PMID 37189525, 2023).
Fabry disease (2 papers, 2020 to 2021). Fabry disease (FD) is a progressive, inherited, multisystemic lysosomal storage disease characterized by specific neurological, cutaneous, renal, cardiovascular, cochleo-vestibular and cerebrovascular manifestations. "These manual tools consisted of scores, decision trees and guidelines for the diagnosis of Marfan syndrome, Fabry disease, diseases with recurrent wheals or angioedema, HNF1B-related disease, familial chylomicronemia syndrome and Niemann-Pick disease Type C." (PMID 32299466, 2020).
familial juvenile hyperuricemic nephropathy (2 papers, 2024 to 2025). "Patients with HNF1B haploinsufficiency may present with renal hypoplasia and dysgenesis, familial juvenile hyperuricemic nephropathy, glomerulocystic kidney disease, and renal interstitial fibrosis, ultimately leading to CKD." (PMID 39337310, 2024).
Hepatic steatosis (2 papers, 2022 to 2023). Steatosis is a term used to denote lipid accumulation within hepatocytes. "Our findings are in agreement with previous studies in regard to the reduced HNF1B associated with hepatic steatosis." (PMID 35460694, 2022). "Additionally, significant hepatic lesions (unexplained, otherwise with detailed workup) in the form of hepatic steatosis with enzymes more than five times the upper limit of normal were diagnosed as well as hypomagnesemia, probably related to the HNF1B mutation." (PMID 37511676, 2023). "In the present study, we identified novel targets of miR-200c, Hnf1b, and ApoO, regulating TG secretion and mitochondrial function, providing previously unappreciated mechanisms for alcoholic hepatic steatosis." (PMID 35460694, 2022). "In addition, HNF1B is closely related to other obesity comorbidities (such as fatty liver disease)." (PMID 37511676, 2023).
Hypoglycemia (2 papers, 2024 to 2025). A decreased concentration of glucose in the blood. "Our case highlights the relationship between congenital hypopituitarism and HNF1β gene deletion in 17q12 deletion syndrome as a severe neonatal cholestasis etiology, emphasizing the need to be especially vigilant in cases with associated hypoglycemia." (PMID 40256398, 2025).
Infertility (2 papers, 2013 to 2021). "Some men with the HNF1B mutations have malformations in the reproductive tract including epididymal cysts, agenesis of the vas deferens, or infertility due to abnormal spermatozoa." (PMID 24386569, 2013).
Lung squamous cell carcinoma (2 papers, 2018 to 2020). "In Lung squamous cell carcinoma (LUSC), HNF1B was correlated with the macrophage infiltration (r=0.335, p=5.53e-14)." (PMID 33173410, 2020). "HNF-1B was completely negative in hepatocellular, colorectal, breast, and lung squamous cell carcinomas." (PMID 30065837, 2018).
Meckel Gruber syndrome (2 papers, 2023 to 2024). "As a differential diagnosis ADPKD, congenital nephrosis of the finnish type, Meckel Gruber syndrome, Trisomy 13 and Beckwith Wiedemann, as well as loss of HNF1B can appear prenatally with a similar phenotype with enlarged hyperechogenic kidneys." (PMID 37535131, 2024).
mesonephric adenocarcinoma (2 papers, 2015 to 2019). An adenocarcinoma of the cervix or the vagina arising from mesonephric remnants. "In a second study, focused on the immunohistochemical analysis of seven mesonephric adenocarcinomas, expression of HNF-1β was found in 3/7 cases (42.8%)." (PMID 25884453, 2015).
mesothelioma (2 papers, 2020 to 2024). A usually malignant and aggressive neoplasm of the mesothelium which is often associated with exposure to asbestos. "The most common markers included calretinin, CK5/6, WT-1, D2-40, Vimentin, HBME-1, ER, PR, CEA, Ber-EP4, B72.3, and HNF-1β, and the first six were mesothelioma markers with high sensitivity." (PMID 39605894, 2024).
pancreatic adenocarcinoma (2 papers, 2017 to 2020). "Additionally, the combination of HNF1B expression and CD4+ T cell infiltration levels showed prognostic value in cervical squamous cell carcinoma (CESC), brain lower grade glioma (LGG), pancreatic adenocarcinoma (PAAD), rectum adenocarcinoma (READ), sarcoma (SARC)." (PMID 33173410, 2020).
papillary renal cell carcinoma (2 papers, 2020 to 2021). A rare subtype of renal cell carcinoma, arising from the renal tubular epithelium and showing a papillary growth pattern, which typically manifests with hematuria, flank pain, palpable abdominal mass or nonspecific symptoms, such as fatigue, weight loss or fever. "The results of our work on a limited sample set suggest that while in papillary renal cell carcinoma HNF1B functions as an oncogene, in ccRCC and chRCC it may act in a tumour suppressive fashion." (PMID 33051485, 2020).
tuberous sclerosis (2 papers, 2018 to 2025). Hereditary disease characterized by seizures, intellectual disability, developmental delay, and skin and ocular lesions. "Even though the cohort is limited, these data suggest, as somewhat expected, that the worst and most rapid progression of disease was associated with ARPKD, HNF1B-related disease, and tuberous sclerosis." (PMID 39384646, 2025).
Ureteral obstruction (2 papers, 2016 to 2020). Obstruction of the flow of urine through the ureter. "However, HNF-1β expression was suppressed in TECs 7 days after ureteral obstruction." (PMID 27196561, 2016).
ampullary adenocarcinomas (1 paper, 2018). "HNF-1B was highly expressed in adenocarcinomas along the pancreaticobiliary tract, including PDAC, intrahepatic and extrahepatic cholangiocarcinomas, ampullary adenocarcinomas, and gallbladder adenocarcinomas with nuclear and/or cytoplasmic staining pattern." (PMID 30065837, 2018). "Not surprisingly, HNF-1B was strongly immunoreactive with nuclear and/or cytoplasmic patterns in 13 of 15 (86.7%) intrahepatic and extrahepatic cholangiocarcinomas, 13 of 18 (72.2%) ampullary adenocarcinomas, and 13 of 14 (92.9%) gallbladder adenocarcinomas." (PMID 30065837, 2018).
Bartter syndrome type 1 (1 paper, 2026). "One patient was diagnosed with MODY5, caused by a known mutation in the HNF1B gene, and one patient was diagnosed with Bartter syndrome type 1, resulting from a known mutation in the SLC12A1 gene." (PMID 41828581, 2026).
cervical adenocarcinoma (1 paper, 2015). An adenocarcinoma arising from the cervical epithelium. "Limitation of the utility of HNF-1β includes expression in benign glands, which preclude use of this marker in the differential diagnosis of benign lesions and well differentiated p16 negative types of cervical adenocarcinoma." (PMID 25884453, 2015).
cervical squamous cell carcinoma (1 paper, 2020). A squamous cell carcinoma arising from the cervical epithelium. "CD8+ T cells were found to be positively associated with overall survival in the low HNF1B expression group of cervical squamous cell carcinoma (CESC, HR=0.51, p=0.0488) and skin cutaneous melanoma (SKCM, HR=0.665, p=0.0291)." (PMID 33173410, 2020).
chronic pancreatitis (1 paper, 2026). A chronic inflammatory process causing damage and fibrosis of the pancreatic parenchyma. "By integrating a literature review, we discuss the pathophysiology related to hepatocyte nuclear factor 1β (HNF1B) haploinsufficiency, suggesting that chronic pancreatitis may constitute part of the syndrome's clinical spectrum." (PMID 42063794, 2026).
colitis (1 paper, 2024). Inflammation of the colon. "Following the specific suppression of HNF-1β, the majority of HD’s protective actions were nullified; colitis symptoms intensified, intestinal permeability surged, and the expression of TJs and AJs was reduced." (PMID 39650157, 2024). "The outcomes from both AAV and Lentivirus studies concur that HNF-1β is pivotal in HD’s protective influence on the intestinal barrier, with HNF-1β-induced upregulation of DRA playing a key role in mitigating colitis-induced epithelial barrier deficiencies through HD treatment." (PMID 39650157, 2024). "Furthermore, our research indicates that HD enhances the expression of TJs and AJs through the activation of the HNF-1β/DRA pathway, effectively protecting the intestinal barrier from colitis-induced impairments." (PMID 39650157, 2024).
diabetic retinopathy (1 paper, 2020). "In a cohort of 27 adult carriers of a hnf1b mutation with a median age of 35 years, none developed diabetic retinopathy or neuropathy in the follow-up." (PMID 32864159, 2020).
DiGeorge syndrome (1 paper, 2016). "Various promising CNVs have been reported located at 1q21.1 (RBM8A), 16p11.2 (TBX6), 17q12 (LHX1, HNF1B), as well as 22q11 associated with DiGeorge syndrome." (PMID 28003020, 2016).
duodenal atresia (1 paper, 2023). Duodenal atresia is an embryopathy of the cranial intestine that leads to a complete absence of the duodenal lumen. "Although the overexpression of HNF1B has not been demonstrated to be directly associated with duodenal atresia, AP results in the pancreatic tissue completely or incompletely surrounding the duodenum leading to duodenal obstruction." (PMID 37422671, 2023).
endometrial endometrioid carcinoma (1 paper, 2023). "However, subsequent studies have shown that 22-60% of endometrial serous carcinoma (at least focal), 5-35% of endometrial endometrioid carcinoma, a wide range of non-clear cell cervical cancers, and only 78-67% of uterine clear cell carcinomas are positive for HNF1β." (PMID 37383161, 2023).